ADAMTS1 (ADAM metallopeptidase with thrombospondin type 1 motif 1)
Diseases named in the same sentence as ADAMTS1 in open-access papers (continued):
Sharing a sentence is not in itself a finding about the gene and the disease.
tumor (continued). "ADAMTS-1 is anti-angiogenic, whereas MMP9 is highly pro-angiogenic, and can trigger the ‘angiogenic switch’, a process in tumours where the balance of pro- and anti-angiogenic factors swings towards a pro-angiogenic outcome." (PMID 32269093, 2020). "Methylation of ADAMTS1 and BNC1 showed a certain sensitivity and specificity for the early diagnosis of this neoplasia." (PMID 33114412, 2020). "Adamalysins genes/ A distintegrin and metalloproteinase with thrombospondin motifs (ADAMTS) family genes, ADAMTS1 (FC = −9.4, p = 0.009), and ADAMTS5 (FC = −5.7, p = 0.05) were significantly down-regulated in tumours, as compared to controls." (PMID 31292488, 2019). "ADAMTS1 and QKI were identified as possible PCa tumor suppressors, as their expression was down-regulated, respectively, in metastatic CRPC and in poorly differentiated PCa." (PMID 29216878, 2017). "Our results indicate an increased expression of the 87 kDa form of ADAMTS1 in MCF-7 and IBH-7 tumor cells incubated with hATT-CMs vs. hATN- or control-CMs." (PMID 28173833, 2017). "ADAMTS1, as well as ADAMTS8 and 15, all promote tumor growth and metastasis in the MMTV-PyMT model, and predict survival of human basal breast cancer." (PMID 27542270, 2016). "ADAMTS1 (ADAM metallopeptidase with thrombospondin type 1 motif, 1) is a widely expressed matrix metalloproteinase with documented roles in angiogenesis and tumor biology." (PMID 20546609, 2010). "The main findings were that ADAMTS1 altered the blood vessel morphology and TSP1 levels in the tumor xenografts." (PMID 20546609, 2010). "We report that modified expression of ADAMTS1 resulted in markedly changed blood vessel morphology and TSP1 levels in the tumor xenografts, while MVD and pericyte coverage was unaffected." (PMID 20546609, 2010). "The tumor promoting effect is believed to involve the release of growth factors from ECM, and there are studies suggesting that the proteolytic status of ADAMTS1 is of importance for its effect on tumor growth." (PMID 20546609, 2010). "Regarding biological functions, let-7f inhibits tumor cell proliferation, invasion, metastasis, stemness maintenance, and metabolic reprogramming by targeting multiple oncogenes (e.g., MYH9, HMGA2, ADAMTS1, Periostin) and key signaling pathways (e.g., MAPK, Wnt, PI3K/AKT)." (PMID 42293764, 2026). "Although ADAMTS1 has been considered to be a positive regulator of tumor metastasis, the potential role in testicular cancer is not investigated." (PMID 40878842, 2025). "ADAMTS 1 and ADAMTS 9 also have tumour suppressive properties and antiangiogenic effects." (PMID 36982551, 2023). "Moreover, ADAMTS1 positively regulated TGF-β expression, and TGF-β was highly expressed in NSCLC tumor tissues." (PMID 36947712, 2023). "The results showed that the mRNA and protein expressions of ADAMTS1 in tumor tissues were significantly higher than those in adjacent normal tissues." (PMID 36947712, 2023). "MMP-1 and ADAMTS-1 proteolytically release EGF-like ligands, including amphiregulin (AREG), heparin-binding EGF (HB-EGF), and transforming growth factor α (TGF α), from tumor cells." (PMID 36338393, 2022). "The clusters 1, 7 and 8 highly expressed steroidogenic genes STAR as well as tissue remodeling genes HAS1, ADAMTS1 and ADAMTS4, consistent with theca-stromal cells from ovary, which might be included from non-tumor tissues from ovaries." (PMID 34257564, 2021). "Interestingly, ADAMTS1 and CDH5 also appeared significantly induced in the tumor context, suggesting again their direct link during tumor progression." (PMID 32230715, 2020). "Significantly, the expression of ADAMTS1 was upregulated during differentiation of GICs with a similar pattern to endothelial-related CDH5 and ENG genes, supporting the existence of an intrinsic endothelial-like nature within these tumor-promoting cells." (PMID 33396280, 2020).
tumor (continued). "Hence we validated gene expression of MMP1, MMP3, MMP11, MMP13, MMP14, ADAMTS1 and ADAMTS5 genes belonging to metallopeptidase activity, using qPCR in 67 tumours." (PMID 31292488, 2019). "Furthermore, we demonstrated that miR-548k modulating the tumor microenvironment by promoting VEGFC secretion and stimulating lymphangiogenesis through ADAMTS1/VEGFC/VEGFR3 pathways, while promoting metastasis by regulating KLF10/EGFR axis." (PMID 30131072, 2018). "Our results confirmed a pro-inflammatory landscape in the absence of ADAMTS1, correlating with tumour blockade, supporting its novel role as a modulator of the immune cell response." (PMID 30166561, 2018). "For instance, ADAMTS-1 functions as a protumor protease if it is produced by stroma-derived cells, but not when produced by tumor cells." (PMID 28099917, 2017). "In addition, we found that CD147, ADAMTS1 and 9 were all expressed mostly in “spindle cells”, the typical LANA+ KS tumor cells." (PMID 26675551, 2016). "All these data together reinforce the notion that stroma-derived but not tumor ADAMTS1 supported tumor development through a vascular-dependent mechanism." (PMID 27120788, 2016). "Although levels of the protease were still provided by tumor cells, the absence of ADAMTS1 in the host stroma significantly impaired B16F1 tumor growth and metastasis." (PMID 27120788, 2016). "Moreover, CD147, ADAMTS1 and 9 were strongly expressed within AIDS-KS tumor tissues, demonstrating their potential clinical relevance as well as biomarker or therapeutic values." (PMID 26675551, 2016). "This analysis revealed significant levels of Adamts1 in the tumor comparing with B16F1 cells in culture; nevertheless no major changes between WT and ATS1-KO mouse tumors were observed." (PMID 27120788, 2016). "Additional gene expression data of endothelial markers from these tumors also confirmed that alterations depend on the nature of the animal (WT versus ATS1-KO mice) and that the downregulation of tumor Adamts1 did not significantly contribute." (PMID 27120788, 2016). "Again, significant differences were only noted between the animals of different genotypes (WT versus ATS1-KO) but not among those who had altered levels of Adamts1 in the tumor cells." (PMID 27120788, 2016). "Since the absence of Adamts1 occurs in all cells, both neoplasic and stromal, it is not possible to discriminate between the relevance of the protease secreted by tumor cells or by different stromal components." (PMID 27120788, 2016). "Since we observed nuclear ADAMTS-1 on tissue tumor cells and on cells in culture, but not on normal breast luminal cells, further studies can explain if these pathways are altered in tumor cells compared to normal breast cells." (PMID 27764205, 2016). "In contrast, ADAMTS-1 staining was discrete or absent in the tumor stroma, and this discrete or absent staining pattern was more evident in cases with higher grades of malignancy." (PMID 23289900, 2013). "In bone metastasis, acting as a sheddase, ADAMTS1 promotes the release of membrane bound epidermal growth factor (EGF)-like growth factors, including amphiregulin (AREG), heparin-binding EGF (HB-EGF), and transforming growth factor α (TGFα) from tumor cells." (PMID 24213506, 2012). "Since ADAMTS1 is a multifunctional protein mainly acting indirectly on tumor cells by regulating the availability and activity of factors present in the ECM, the constitution of the surrounding ECM is probably of great importance for the net effect of ADAMTS1." (PMID 20546609, 2010). "Decreased levels of ADAMTS1 did not affect tumor take of androgen-dependent LNCaP cells, but strongly inhibited tumor growth rate." (PMID 20546609, 2010). "Methylated ADAMTS1, MGMT, and MAL are suitable as markers for early tumor detection." (PMID 19117505, 2008).
tumor (continued). "Additionally we selected seven other genes, ATF3, ADAMTS1, EGFR, PRNP, IGFBP6, ID4 and FN1, found to be differentially expressed according to tumor subtype and ER+/ER- classification from the tumor-specific differentially expressed gene-set." (PMID 19116033, 2008). "In sharp contrast, ADAMTS-1 mRNA levels were significantly lower in tumour tissues when compared to corresponding nondiseased lung." (PMID 16495931, 2006). "Intriguingly, ADAMTS1 was also shown to promote tumor growth in a xenograft model, but did not influence in vitro growth rates of OSCC cells, suggesting that ADAMTS1 might indirectly promote oral tumorigenesis in vivo." (PMID 38263290, 2024). "More specifically, the requirement of ADAMTS1 for tumor progression in our mouse models, its relationship with stemness and endothelial plasticity features, and its higher expression at earlier stages of UVM, all support the role of ADAMTS1 as a pro-tumorigenic factor for this rare type of tumor." (PMID 32230715, 2020). "In addition, the downregulation of ADAMTS1 in B16F1 tumor cells was not accompanied by relevant changes in their tumorigenic properties." (PMID 27120788, 2016). "Interestingly the anti-angiogenic action ADAMTS1 was not a major contributing factor to total tumor angiogenesis as there was no significant increase in blood vessel density in ADAMTS1 null tumors." (PMID 24213506, 2012). "It is likely that the different proteolytic status of ADAMTS1 protein may not be the only reason for the conflicting roles reported on ADAMTS1 in primary tumor growth and metastasis." (PMID 24213506, 2012). "Since TSP1 is a potent angiogenesis inhibitor, this may explain why the MVD in the tumor xenografts was not affected by altered levels of ADAMTS1." (PMID 20546609, 2010). "However, once tumors were established the LNCaP-19 cells seem to escape from this inhibitory effect of ADAMTS1, since no obvious difference in tumor growth rate was observed." (PMID 20546609, 2010). "Furthermore, ADAMTS-1 and MMP-1 act in concert to not only enhance invasion through the ECM and endothelium but also to promote tumor colonization in the bone microenvironment through an intricate pro-osteolytic signaling cascade that involves tumor cells, osteoblasts, and osteoclasts." (PMID 36338393, 2022). "However, the downregulation of tumor ADAMTS1 did not uncover relevant effects." (PMID 27120788, 2016). "These contrasting findings may result from the auto-proteolytic cleavage of ADAMTS1 with subsequent disparate effects on tumor activity – the full length molecule displays pro-tumor properties while its cleavage products, ADAMTS-1NTF and ADAMTS-1CTF, exhibit anti-tumor activity." (PMID 24999452, 2014). "However, in this study ADAMTS1 was only detected in its latent and full-length active form in both LNCaP and LNCaP-19 tumors, suggesting that this is not the reason to the difference in tumor growth regulation in this model." (PMID 20546609, 2010). "We considered very relevant the lack of differences in Adamts1 expression between tumors generated in WT and in ATS1-KO animals, although tumor progression was clearly affected." (PMID 27120788, 2016).
cancer (84 papers, 2005 to 2025). A tumor composed of atypical neoplastic, often pleomorphic cells that invade other tissues. "ADAMTS1 was shown to remodel the extracellular matrix and has been implicated in angiogenesis, embryogenesis, wound repair, and cancer development." (PMID 36341352, 2022). "Consistent with ADAMTS1, enrichment analysis also revealed that tumors with lower levels of A2M were strongly associated with poor survival and cancer metastasis." (PMID 35625488, 2022). "ADAMTS1 is implicated in many physiological events, such as angiogenesis inhibition, various inflammatory processes and development of cancer cachexia." (PMID 28569793, 2017). "Whereas genes likely to be associated with development of cancer cachexia, such as ADAMTS1, and the key mediator of inflammatory response, such as IL1B, were down-regulated in SP cells." (PMID 27725724, 2016). "ADAMTS-1 has been detected in a variety of carcinomas, and an imbalance of ADAMTS-1 expression is associated with several tumors." (PMID 27764205, 2016). "Cancer associated fibroblasts which are activated by cancer cells also overexpress inflammatory mediators as well as serglycin and a disintegrin and metalloproteinase with thrombospondin motifs 1 (ADAMTS1), promoting cancer cell invasion." (PMID 24455486, 2014). "It was found that the sustained ADAMTS1 upregulation in NAFs precocultured with cancer cells correlates with an epigenetic mechanism involving the loss of ADAMTS1 promoter-associated EZH2 binding and the corresponding H3K27 trimethylation." (PMID 22514714, 2012). "The current report demonstrates that cancer-associated fibroblasts (CAFs) secreted ADAMTS1 to promote cancer cell invasion." (PMID 22514714, 2012). "ADAMTS1 has been implicated in the malignant transformation of cancer, including metastasis." (PMID 40878842, 2025). "Survival maps from the GEPIA2 database showed that among the 33 analyzed cancer types, increased expressions of ADAMTS1, L1CAM, and EGFR were only significantly associated with poor survival in HNSCC, implying the critical and specific role of the ADAMTS1-L1CAM-EGFR axis in HNSCC progression." (PMID 38263290, 2024). "We suggest that ADAMTS1-induced dissemination of cancer cells in vivo might be caused by VCAN-mediated invasion promotion and anoikis resistance." (PMID 39333870, 2024). "Low ADAMTS1 expression has been linked to tumorigenesis in some cancers." (PMID 30004416, 2018). "ADAMTS1 (a disintegrin and metalloprotease with thrombospondin motifs 1) is a zinc-binding metalloprotease broadly expressed by several adult tissues, and is implicated in tissue remodeling during cancer development and progression." (PMID 29212212, 2017). "Importantly this last report has been the only one, as far as we know, that included an Adamts1-deficient mouse in a cancer-related study." (PMID 27120788, 2016). "Indeed, the most intriguing question is how the loss of EZH2 binding to ADAMTS1 promoter is sustained in cancer cell-cocultured NAFs after the removal of cancer cells." (PMID 22514714, 2012). "Thus, it's unlikely that DNA methylation governs the differential expression of ADAMTS1 in cancer-associated fibroblasts." (PMID 22514714, 2012). "To uncover the effect of ADAMTS1 C‐mannosylation on cancer progression, we evaluated VM formation, which is closely correlated with cancer progression." (PMID 40878842, 2025). "Among these, ADAMTS1 is the most extensively studied member that regulates cancer progression via targeting specific substrates within the ECM, such as proteoglycans and growth factors." (PMID 39333870, 2024). "ADAMTS1 is one kind of ECM protease, which is implicated in a wide range of mechanistic pathways involved in cancer progression and metastasis of different cancer types." (PMID 39333870, 2024). "Conflicting reports have shown both upregulation and downregulation of ADAMTS1 in different cancer types compared to normal tissues, implying both pro- and anti-tumorigenic activities of ADAMTS1." (PMID 38263290, 2024).
cancer (continued). "For example, versican, one of the ADAMTS1 substrates, was reported to promote invasive phenotypes of gastric and ovarian cancer cells." (PMID 38263290, 2024). "ADAMTS1 is one kind of ECM protease which exerts diverse impacts on the progression of different cancer types." (PMID 38263290, 2024). "VCAN and ACAN are recognized as substrates of ADAMTS1, influencing cancer progression or metastasis." (PMID 39333870, 2024). "Nineteen ADAMTS proteases have so far been identified in humans, and the dysregulated expression of ADAMTS1 is the best characterized in cancer." (PMID 38263290, 2024). "Genes with known implications in cancer, such as MMP-13, KRT84, OLFM4, GJA1, AMOT and ADAMTS1, were strongly linked to DSG3 overexpression." (PMID 38067138, 2023). "A disintegrin-like and metalloproteinase with thrombospondin type 1 motifs (ADAMTS1) is a protease involved in fertilization, cancer, cardiovascular development, and thoracic aneurysms." (PMID 36813235, 2023). "As for the downstream target, we suggested that ADAMTS1 decreased cancer development of LUAD by incorporating α2-macroglobulin (A2M)." (PMID 35625488, 2022). "ADAMTS1 has been indicated to alter the infiltration of immune cells in B16F1 cancer by increasing CD3+ T cells and CD11b+ myeloid cells with a decreased CD163 expression in ADAMTS1-deficient mice." (PMID 35625488, 2022). "A recent study also showed that ADAMTS1 decreases cancer migration by regulating the spatiotemporal dynamics of Cdc42 activity." (PMID 35625488, 2022). "The current study aimed to investigate the role of ADAMTS1 on cancer progression and immunity of TME." (PMID 35625488, 2022). "Our findings revealed that ADAMTS1 was a target of hypoxia, which acts as a pivotal regulator in stimulating the development of an aggressive phenotype in cancer." (PMID 35625488, 2022). "From the top down- and up-regulated DEG, four genes (ADAMTS1, FGF1, G0S2 and TP63) were also closely associated with cancer pathways according to the literature." (PMID 35840561, 2022). "Perturbations in ADAMTS1 evoke significant changes that ultimately promote cancer development and metastatic progression." (PMID 32629802, 2020). "ADAMTS-1, −3, −5, −8 and −18 were down-regulated in cancer tissues whilst ADAMTS-4, −6, −10 and −14 were overexpressed in cancer tissues." (PMID 33063817, 2020). "The extracellular protease ADAMTS1 has already been reported to contribute to the plasticity of cancer cells." (PMID 33396280, 2020). "In particular, Adamts1 expression was markedly increased, whereas Adamts2 and -8 expressions, which are presumably important in cancer cell invasion, increased in the later stages of differentiation." (PMID 31297611, 2020). "Expression of ADAMTS1 has been positively correlated with disease progression in cancers of different origins." (PMID 30004416, 2018). "Some members (ADAMTS2, 4, 6, and 14) are shown to be manifestly upregulated in cancer tissues, whereas others (ADAMTS1, 5, 8, 9, 10, 13, 15, and 18) are downregulated." (PMID 27463966, 2016). "ADAMTS genes show epigenetic silencing (ADAMTS1, 8, 9, 12, 19) or genetic inactivation by DNA mutations (ADAMTS15, 18) in cancer." (PMID 27542224, 2016). "Western blot analysis further supported the RT-PCR findings, revealing in addition the degradation of ADAMTS-1 and -20 in cancer." (PMID 25786261, 2015). "From the results of our study in CRC tissue and cells, we conclude that ADAMTS-4 and -5 expression positively correlates with cancer progression, whereas the anti-angiogenic ADAMTS-1 and -20 were found to be down-regulated and degraded." (PMID 25786261, 2015). "RT-PCR analyses indicated that ADAMTS-1 was down-regulated in cancer specimens of any stage compared to the healthy colon, with the greatest decrease to about 20% in stage A specimens." (PMID 25786261, 2015).